TPTEP2-CSNK1E (TPTEP2-CSNK1E readthrough)
Synonyms: LOC400927-CSNK1E
Gene: Protein-coding gene on chromosome 22 (38,291,918 to 38,398,522, reverse strand). Ensembl gene ENSG00000283900.
Genetic constraint (gnomAD): Loss-of-function variants: 17 observed, 43.37 expected, observed/expected ratio (o/e) 0.39, 90% interval 0.27 to 0.59. The upper end of that interval is the gene's LOEUF score, 0.59, which puts it in group 2 of 6, group 1 being the genes least tolerant of losing a copy. Missense variants: 386 observed, 589.45 expected, observed/expected ratio (o/e) 0.65, 90% interval 0.6 to 0.71. Synonymous variants: 241 observed, 238.58 expected, observed/expected ratio (o/e) 1.01, 90% interval 0.91 to 1.12.